ABI3 (ABI family member 3)
Diseases named in the same sentence as ABI3 in open-access papers (continued):
Sharing a sentence is not in itself a finding about the gene and the disease.
thyroid tumor (3 papers, 2011 to 2023). A benign or malignant neoplasm affecting the thyroid gland. "To test the possibility that ABI3 expression is associated with thyroid tumor malignancy, we examined mRNA expression in a panel of thyroid tumors specimens and normal thyroid." (PMID 21223585, 2011). "It has been reported that ABI3 expression is decreased in thyroid tumors, and ectopic expression of ABI3 inhibits tumor formation." (PMID 36926204, 2023). "Taken together, the results presented in this manuscript clearly indicate that mechanism governing ABI3 expression in thyroid tumors involves methylation/demethylation at specific CpG sites located at the promoter region of ABI3, designed as cDMR." (PMID 27036019, 2016). "We previously reported that ABI3 expression is lost in thyroid tumors and its re-expression in thyroid cells lines significantly suppresses cell growth in vitro and tumor growth in vivo." (PMID 27036019, 2016). "As lower expression of NKX2-1 is correlated with progressive dedifferentiation of thyroid tumors, we next used qPCR to evaluate the expression levels of NKX2-1 in thyroid samples and correlated NKX2-1 and ABI3 expression." (PMID 27036019, 2016). "Although the level of NKX2-1 expression was comparable in thyroid tumors, a positive correlation was observed between ABI3 and NKX2-1 expression in thyroid tumors (r = 0.4057 and P = 0.0179)." (PMID 27036019, 2016).
coronary atherosclerosis (2 papers, 2020 to 2024). Atherosclerosis of the coronary vasculature. "Previous research has demonstrated that the ABI3 variant is associated with a range of cardiovascular traits, including hypertension, ischemic heart disease, and coronary atherosclerosis, based on phenome-wide association studies (PheWAS)." (PMID 38062164, 2024). "ABI3 variant rs28394864 was significantly associated with cardiovascular (e.g. (hypertension, ischemic heart disease, coronary atherosclerosis, angina) and immune-related trait asthma." (PMID 33152005, 2020). "The associations of ABI3 variant rs28394864 with cardiovascular traits (hypertension, ischemic heart disease, coronary atherosclerosis, angina), and asthma are novel findings from this study." (PMID 33152005, 2020). "In addition to APOE variants and rs646776, ABI3 variant rs28394864 was also associated with cardiovascular traits, such as hypertension (p = 1.60 x 10−13), ischemic heart disease (p = 4.58 x 10−9), coronary atherosclerosis (p = 6.47 x 10−10), and angina (p = 6.51 x 10−9)." (PMID 33152005, 2020).
glioblastoma (2 papers, 2011 to 2015). The most malignant astrocytic tumor (WHO grade IV). "The authors showed that ABI3 expression reduces cell motility and metastatic dissemination of a highly metastatic murine fibroblast transformed by v-Src (SRD) and the human glioblastoma cell line (U87 MG), while it did not interfere with cellular growth." (PMID 21223585, 2011).
glioma (2 papers, 2023 to 2025). A benign or malignant brain and spinal cord tumor that arises from glial cells (astrocytes, oligodendrocytes, ependymal cells). "ABI3 has also been reported as a key gene of disulfidptosis in low-grade gliomas, which is associated with patient prognosis and immune microenvironment." (PMID 40548122, 2025). "Characterized by elevated expression in glioma, ABI3 is implicated in the migration, invasion, and disulfidptosis of glioma cells." (PMID 38162649, 2023). "In order to validate ABI3 expression levels in glioma tissues, we conducted immunohistochemistry experiments on tissue microarrays made from glioma specimens collected from Xiangya Hospital (containing 11 paraneoplastic tissues and 84 diffuse glioma samples)." (PMID 38162649, 2023). "After extensive experimentation, we have definitively determined that the ABI3 protein is intricately connected to vital mechanisms in glioma cells, encompassing movement, infiltration, and the initiation of epithelial-mesenchymal transition." (PMID 38162649, 2023). "To elucidate the biological role of ABI3 in glioma, we initially assessed the mRNA expression levels of ABI3 across six glioma cell lines, namely HGS683, SHG44, U251, LN229, U87 and A172." (PMID 38162649, 2023). "Based on our empirical evidence, we observed a successful reduction in the expression of the ABI3 gene, which led to a significant inhibition of migration and invasion abilities in glioma cells." (PMID 38162649, 2023). "Significantly, ABI3 expression in glioma tissues was notably higher when compared to their normal counterparts." (PMID 38162649, 2023). "Utilizing the GEPIA2 online platform, we assessed the expression profile of ABI3 in glioma and normal tissue samples." (PMID 38162649, 2023). "Subsequent scratch assays and Transwell matrigel invasion assays revealed that ABI3 downregulation notably attenuated the migratory and invasive capabilities of SHG44 and U251 glioma cells." (PMID 38162649, 2023). "Moreover, there was a significant increase in protein expression of ABI3 in WHO grade III (P< 0.05) and grade IV gliomas (P< 0.001) compared to WHO grade II gliomas." (PMID 38162649, 2023).
Gliosis (2 papers, 2022 to 2023). Gliosis is the focal proliferation of glial cells in the central nervous system. "Weighted gene co-expression network analysis (WGCNA) identified several gene modules correlating the Abi3-Gngt2 genotype with the gliosis phenotype." (PMID 35897046, 2022).
Obesity (2 papers, 2022 to 2025). Accumulation of substantial excess body fat. "Overall, these findings suggest that the loss of ABI3 function may drive obesity through impairments to energy expenditure." (PMID 36620768, 2022). "Therefore, the change in microglia number could indicate that the loss of Abi3 might induce obesity through altered microglia function within the mediobasal hypothalamus." (PMID 36620768, 2022). "In this report, we aim to address this knowledge gap by investigating the impact of Abi3 deletion on measures of systemic metabolism and obesity." (PMID 36620768, 2022). "This likely suggests that the obesity in Abi3–/– mice induced impairments to systemic glucose regulation, as is typically observed in obese mice." (PMID 36620768, 2022). "Elevated leptin and cholesterol levels are characteristic of obesity, and therefore these results further demonstrate the extent of the obese phenotype observed in Abi3–/– mice." (PMID 36620768, 2022). "Furthermore, our study has now demonstrated how deletion of Abi3 gene locus can have dramatic impacts on the seemingly distinct disease states of obesity and neurodegeneration, likely due to disruptions in microglia functions." (PMID 36620768, 2022). "Given the importance of microglia within the mediobasal hypothalamus to obesity, in conjunction with our sequencing analysis, we evaluated whether Abi3–/– mice had altered microglia number within the mediobasal hypothalamus or any other CNS region." (PMID 36620768, 2022). "We found that MORC3, NUP62, CGAS, ABI3, and RPA2 were highly expressed in lean individuals, where as LMNA, ID2, CDKN1A, TENT4B, MME, and MYC were upregulated in the PBMCs of individuals with obesity." (PMID 40847086, 2025).
thyroid (2 papers, 2011 to 2016). "In this study, we observed that ABI3 expression is lost or reduced in most malignant samples, compared to benign thyroid samples." (PMID 21223585, 2011). "To test this hypothesis, we investigated the expression of ABI3 in thyroid benign and malignant lesions." (PMID 21223585, 2011).
asthma (1 paper, 2020). "ABI3 variant was also associated with asthma in the UKB cohort (p = 1.77 x 10−13)." (PMID 33152005, 2020).
atherosclerosis (1 paper, 2024). A disease characterized by the build-up of fatty material and calcium deposition in the arterial wall resulting in partial or complete occlusion of the arterial lumen. "In our study, we have further explored the underlying mechanism of ABI3 in atherosclerosis progression." (PMID 38062164, 2024). "Here, we investigated whether ABI3 participates in macrophage senescence induced by Hcy, an independent risk factor for atherosclerosis." (PMID 38062164, 2024). "We next focused on the effect of ABI3 in atherosclerosis progression since it has not been previously investigated." (PMID 38062164, 2024).
Atherosclerotic lesion (1 paper, 2024). A lesion associated with atherosclerosis, a multifactorial and multipart progressive disease manifested by the focal development within the arterial wall of lesions, that ranges from the development of a fatty streak, plaque progression, and plaque disruption. "To further validate these results, we investigated the expression levels of ABI3 in macrophages of advanced atherosclerotic lesions in vivo, ApoE−/− mice were fed with a high-methionine diet for 4 or 18 weeks to induce early or advanced atherosclerotic lesions as reported." (PMID 38062164, 2024).
autoimmune thyroid disease (1 paper, 2023). Inflammatory disease of the thyroid gland due to autoimmune responses leading to lymphocytic infiltration of the gland. "GSEA enrichment analysis revealed that high ABI3 expression was predominantly associated with immune-activated processes, such as Allograft rejection, Autoimmune thyroid disease, and Graft−versus−host disease." (PMID 37942289, 2023).
colorectal cancer (1 paper, 2023). A primary or metastatic malignant neoplasm that affects the colon or rectum. "Interestingly, within the subtypes of Non-Small Cell Lung Cancer and Colorectal Cancer, ABI3 expression was most abundant within immune cells." (PMID 37942289, 2023).
leukemia (1 paper, 2016). A malignant (clonal) hematologic disorder, involving hematopoietic stem cells and characterized by the presence of primitive or atypical myeloid or lymphoid cells in the bone marrow and the blood. "Although ABI3 was previously reported as methylated in a subset of patients with leukemia, our results differ from the previous study in which the five CpG sites, located within intron 1 of ABI3 gene, were fully methylated and associated with decreased gene expression." (PMID 27036019, 2016). "The next step was to determine the potential link between ABI3 expression and methylation status of the 5 CpG sites located within intron 1 of the ABI3 gene (designated IR), which was previously identified as methylated in leukemia." (PMID 27036019, 2016).
Lewy body disease (1 paper, 2020). "In this study, we addressed this knowledge gap by testing the association of ABI3_rs616338-T and PLCG2_rs72824905-G in purely autopsy-confirmed cohorts of 973 patients with Lewy body disease (LBD-NP) and 1040 with PSP, compared to 3351 controls." (PMID 33092647, 2020). "In this study, we tested the effects of ABI3_rs616338-T and PLCG2_rs72824905-G on disease risk in autopsy cohorts comprised of 973 patients diagnosed neuropathologically with Lewy body disease (LBD-NP) and 1040 with progressive supranuclear palsy (PSP), compared to 3351 controls." (PMID 33092647, 2020).
malignant glioma (1 paper, 2017). A grade III or grade IV glioma arising from the central nervous system. "Other authors did not describe significant changes in the phosphorylation status of either AKT or in MAPK in malignant glioma cells following ABI3 expression." (PMID 28978070, 2017).
prion disease (1 paper, 2026). A transmissible disease that is caused by a protein that is able to induce abnormal folding of normal cellular proteins, leading to characteristic spongiform brain changes, which are associated with neuronal loss without an inflammatory response. "RNA-seq analysis revealed that hypothalamic CYTB, ATP6, COX, ABLIM1, and ABI3 were significantly upregulated in IM group, whereas SHISA7 and PTPRO were significantly downregulated, with notable enrichment in prion disease, oxidative phosphorylation, and thermogenesis pathways." (PMID 41715947, 2026).
proteinopathy (1 paper, 2022). "Because Abi3 is present in both neurons and microglia, its role in non-cell autonomous and cell autonomous signaling in AD proteinopathy and disease progression could be equally important." (PMID 35897046, 2022).
α-synucleinopathies (1 paper, 2018). "It is therefore possible the ABI3 and PLCG2 variants may also influence risk of other neurodegenerative diseases including primary tauopathies and synucleinopathies." (PMID 30326945, 2018).
tumor (15 papers, 2011 to 2025). "Variants of ABI3 BP occur in both tumor groups, and this gene encodes an ECM protein that promotes cell adhesion and ECM assembly." (PMID 40446009, 2025). "The generated heatmap demonstrated that practically all immunoreactive genes were co-expressed with ABI3, and the plurality of these genes exhibited a strong and positive association with ABI3 in all tumor types, with the exception of DLBC." (PMID 37942289, 2023). "In summary, we here demonstrated that the non-phosphorylated form of ABI3 might be associated with its tumor suppressor effects and also propose a mechanism by which ABI3 links with PI3K/AKT with WRC." (PMID 28978070, 2017). "In addition, ectopic expression of ABI3 in metastatic cell lines caused a marked reduction in cell motility and exhibited significant reduction in tumor metastatic potential in vivo." (PMID 21223585, 2011). "Therefore, although ABI3 is considered a tumor suppressor, the phosphorylated form of ABI3 may be associated with cancer development by activating WRC." (PMID 36926204, 2023). "Our findings substantiate ABI3 as a reliable prognostic indicator for numerous cancers, implicating its significant functions in tumor immunity through influencing immune cell infiltration, TMB, and MSI." (PMID 37942289, 2023). "Findings: ABI3 expression and its ability to predict prognosis varied distinct tumor, with particularly high expression observed in Tprolif cells and monocytes/macrophages." (PMID 37942289, 2023). "Collectively, these findings imply that ABI3 expression was tightly interwoven with immune infiltration of tumor cells, affects patient prognosis, and introduces novel targets for the creation of immunomodulatory agents." (PMID 37942289, 2023). "Initially, we scrutinized the expression level of ABI3 in neoplasms on the grounds of TCGA and GTEx data." (PMID 37942289, 2023). "On the other hand, weak ABI3 staining was detected in normal breast tissue samples, whereas moderate staining was observed in tumor tissues." (PMID 37942289, 2023). "To ascertain the nexus between ABI3 expression and facets of the tumor microenvirons, we gauged stromal indices, immune metrics, and ESTIMATE values transversely across neoplastic entities." (PMID 37942289, 2023). "The IHC staining of ABI3 was observed to be moderate in normal lymph node tissues, whereas it was found to be strong in tumor tissues." (PMID 37942289, 2023). "As the majority of investigations regarding ABI3’s involvement in neoplasms focusing on singular malignancies, a comprehensive pan-cancer examination of associations between ABI3 and diverse cancers remains unexplored." (PMID 37942289, 2023). "The experimental data demonstrated a significant diminution in ABI3 protein expression in paraneoplastic tissues relative to tumor tissues." (PMID 38162649, 2023). "Regarding transcription, we initially utilized the TCGA and GTEx databases to investigate ABI3 expression levels in neoplasms compared to their corresponding normal tissues." (PMID 37942289, 2023). "Our study suggests a potential key role for FAT10 in the tumor-inducing function of phosphorylated ABI3." (PMID 36926204, 2023). "In this investigation, we utilized publicly-funded cancer genomics programs and repositories to explore the landscape of different tumor types based on ABI3 expression, with the aim of uncovering its potential role in tumorigenesis." (PMID 37942289, 2023). "ABI3 expression exhibited varying correlations with immune regulatory factors, immune cell infiltration, tumor microenvironment, TMB, and MSI across different cancer types, influencing tumor immunity differently." (PMID 37942289, 2023). "Here, using proteome-profiling array, we found that the tumor suppressive effects of ABI3 reduces phosphorylation of AKT and GSKβ." (PMID 28978070, 2017). "ABI3 functions as a tumor suppressor inhibiting ectopic metastasis of tumor cells and its expression is often lost in invasive cancer cell lines." (PMID 24932473, 2014).